ODF2 (outer dense fiber of sperm tails 2)
Description:
Seems to be a major component of sperm tail outer dense fibers (ODF). ODFs are filamentous structures located on the outside of the axoneme in the midpiece and principal piece of the mammalian sperm tail and may help to maintain the passive elastic structures and elastic recoil of the sperm tail. May have a modulating influence on sperm motility. Functions as a general scaffold protein that is specifically localized at the distal/subdistal appendages of mother centrioles. Component of the centrosome matrix required for the localization of PLK1 and NIN to the centrosomes. Required for the formation and/or maintenance of normal CETN1 assembly.
Synonyms: ODF84; CT134; ODF2/1; ODF2/2
Tractability: PROTAC: UniProt records ubiquitination sites on it; ubiquitination databases record sites on it; its protein half-life has been measured.
Gene: Protein-coding gene on chromosome 9 (128,455,186 to 128,501,292, forward strand). Ensembl gene ENSG00000136811.
Subcellular location: Cytoplasm, cytoskeleton, microtubule organizing center, centrosome; Cell projection, cilium; Cytoplasm, cytoskeleton, microtubule organizing center, centrosome, centriole; Cytoplasm, cytoskeleton, spindle pole; Cell projection, cilium, flagellum
Subcellular location (Human Protein Atlas): Basal body; Centrosome; Connecting piece; Primary cilium; Calyx; Microtubules; Mid piece; Principal piece; Vesicles
Pathways (Reactome):
Cell Cycle: AURKA Activation by TPX2; Loss of Nlp from mitotic centrosomes; Loss of proteins required for interphase microtubule organization from the centrosome; Recruitment of NuMA to mitotic centrosomes; Recruitment of mitotic centrosome proteins and complexes; Regulation of PLK1 Activity at G2/M Transition
Organelle biogenesis and maintenance: Anchoring of the basal body to the plasma membrane
Gene Ontology:
Molecular function: protein binding; structural molecule activity
Biological process: centriole-centriole cohesion; cilium organization; intracellular protein localization; regulation of cilium assembly
Cellular component: centriolar subdistal appendage; centriole; centrosome; nucleus; cytosol; sperm flagellum; sperm midpiece; sperm principal piece; cilium; motile cilium; spindle pole
Genetic constraint (gnomAD): Loss-of-function variants: 44 observed, 100.38 expected, observed/expected ratio (o/e) 0.44, 90% interval 0.34 to 0.56. The upper end of that interval is the gene's LOEUF score, 0.56, which puts it in group 2 of 6, group 1 being the genes least tolerant of losing a copy. Missense variants: 768 observed, 1,032.4 expected, observed/expected ratio (o/e) 0.74, 90% interval 0.7 to 0.79. Synonymous variants: 337 observed, 396.3 expected, observed/expected ratio (o/e) 0.85, 90% interval 0.78 to 0.93.
Homologues: Orthologues: macaque ODF2 (90% identical), rabbit ODF2 (89% identical), pig ODF2 (89% identical), chimpanzee ODF2 (88% identical), rat Odf2 (88% identical), dog ODF2 (87% identical), mouse Odf2 (86% identical), guinea pig ODF2 (85% identical), tropical clawed frog odf2 (51% identical), zebrafish odf2a (47% identical), zebrafish odf2b (38% identical). Paralogues in human: ODF2L (21% identical).
Diseases named in the same sentence as ODF2 in open-access papers:
ODF2 is named in the same sentence as 17 diseases in open-access papers, as found by Europe PMC text mining. Sharing a sentence is not in itself a finding about the gene and the disease. The quoted sentences say what the papers report.
asthenozoospermia (6 papers, 2018 to 2025). "It has been reported that patients with ODF2 deficiency and asthenozoospermia exhibit multiple abnormalities in sperm flagella morphology (MMAF)." (PMID 37240164, 2023). "In mice, disrupting ODF2 expression lowers sperm motility, which is consistent with the characteristics of asthenozoospermia." (PMID 38111731, 2023). "The disruption of ODF2 expression in mice reduced sperm motility, and is compatible with asthenozoospermia characteristics." (PMID 34336830, 2021). "Future work will examine more Odf2 cKO mice through the disruption of different exons to identify the precise function of ODF2 in men with asthenozoospermia." (PMID 29168316, 2018). "To analyse the function of ODFs in asthenozoospermia, we excised exons 6 and 7 of the Odf2 gene by prm1‐cre to disrupt the formation of ODFs in Odf2flox/flox mice." (PMID 29168316, 2018). "The conditional disruption of Odf2 expression in mice led to reduced sperm motility and the characteristics of asthenozoospermia." (PMID 29168316, 2018).
male infertility (5 papers, 2019 to 2025). The inability of the male to effect fertilization of an ovum after a specified period of unprotected intercourse. "Male infertility was attributed to Odf2 haploinsufficiency in spermatozoa, which then disrupted the connection between the centrosome-derived segmented column and flagellar outer dense fibres and caused neck-midpiece separation." (PMID 31582806, 2019). "This section will briefly highlight the role of the eight (TNP1, TNP2, PDHA2, LDHC, SPINK2, ODF1, ODF2, and PCDHB3) common DEGs in male infertility as obtained from our findings." (PMID 35207567, 2022). "Knockouts of EL52, AKAP4, ODF2 and HSPA2 showed phenotypic alterations in sperm physiology and morphology, which resulted in male infertility." (PMID 34697378, 2021). "Collectively, these results indicated that these proteins AKAP4, ODF1, ODF2, GAPDHS, SPESP1, and ACTRT2 were significantly down-regulated after heat treatment of scrotum, suggesting that these proteins may serve as the biomarkers for scrotal heat treatment-induced male infertility." (PMID 32787870, 2020).
infertile (3 papers, 2010 to 2019). "Patients with severe infertility due to Odf2 haploinsufficiency can survive to adulthood and will be diagnosed with a type of teratozoospermia." (PMID 31582806, 2019). "Here we report that XL169 Odf2+/- chimaeric male mice with a high percentage chimaerism are infertile and display a novel abnormal sperm tail phenotype." (PMID 20550699, 2010). "Further studies are necessary to show that ICSI in humans, using headneck sperm cells, is viable and could be an alternative for infertile patients suffering from Odf2-DDS." (PMID 31582806, 2019). "ICSI using human headneck sperm cells could be an alternative for infertile patients suffering from Odf2-DDS." (PMID 31582806, 2019). "Dissimilar to the previous report 25, these cKO mice were not expected to exhibit infertility, possibly due to the 10–30% of WT Odf2 mRNA that was detected in the testicular tissue." (PMID 29168316, 2018). "In the course of our investigation of Odf2 and its expression and function in male germ cells we had used a different Odf2+/- ES cell line, XL169, and we observed that in contrast to our RO072 Odf2+/- chimaeric results, high percentage XL169 chimaeric males were all infertile." (PMID 20550699, 2010).
Hepatitis (1 paper, 2009). Inflammation of the liver. "The levels of zinc alpha glycoprotein (ZAG), membrane associated guanylate kinase 2 and ODF2 were significantly lower in the urine of a fulminant hepatitis E patient compared to a patient with mild hepatitis due to HEV." (PMID 19860894, 2009).
hepatocellular carcinoma (1 paper, 2025). A malignant tumor that arises from hepatocytes. "Here, we dissected PST's mode of action using knockouts of plectin (PLEC) and ODF2 in SNU-475 hepatocellular carcinoma (HCC) cells." (PMID 41467448, 2025).
microcephaly (1 paper, 2013). A congenital or acquired developmental disorder in which the circumference of the head is smaller than normal for the person's age and sex. "Although the gene encoding ODF2 is not currently linked to microcephaly, the protein is linked to several microcephaly proteins and involved in cellular processes proposed to be deficient in microcephaly." (PMID 24153002, 2013).
obstructive hydrocephalus (1 paper, 2025). An abnormal accumulation of cerebrospinal fluid within the ventricles of the brain that occurs as a consequence of an obstruction at any location within the ventricular system that prevents cerebrospinal fluid flowing into the subarachnoid space. "The structural integrity of the basal bodies is further compromised in models lacking outer dense fiber protein 2 (Odf2) and Na+/H+ exchanger regulatory factor 1 (NHERF1), leading to decreased cilia density or motility, and non-obstructive hydrocephalus." (PMID 40722587, 2025).
varicocele (1 paper, 2015). A condition characterized by the dilated tortuous veins of the spermatic cord with a marked left-sided predominance. "ODF2 was overexpressed with high abundance in the unilateral varicocele group." (PMID 25890347, 2015).
tumor (3 papers, 2020 to 2023). "EZH2, HMGB3 and UCK2 expressed higher in tumor compared with normal tissues, while NOTCH2 and ODF2 expressed lower in tumor compared with normal tissues." (PMID 32699528, 2020). "For different tumor status, EZH2 and ODF2 expressed differently." (PMID 32699528, 2020). "Although the majority of CTA peptides were only found to be unique in one patient, we identified multiple peptides derived from CTA-associated genes that were present in a substantial portion of patients independent of the tumor entity (e.g. ATAD2, SPAG9, ODF2, and KIAA0100)." (PMID 37532709, 2023).
cancer (1 paper, 2013). A tumor composed of atypical neoplastic, often pleomorphic cells that invade other tissues. "ODF2 cancer/testis gene was found as a de novo transcriptional target of hypoxia." (PMID 23826488, 2013).
ODF2 also shares sentences with these, for which no sentence is quoted: Azoospermia (1 paper); Bardet-Biedl syndrome (1); ciliopathy (1); Hirschsprung disease (1); Pleural effusion (1); teratozoospermia (1); testicular embryonic carcinoma (1).